RBM34 (RNA binding motif protein 34)
Synonyms: KIAA0117
Tractability: PROTAC: UniProt records ubiquitination sites on it; ubiquitination databases record sites on it; its protein half-life has been measured.
Gene: Protein-coding gene on chromosome 1 (235,131,183 to 235,161,293, reverse strand). Ensembl gene ENSG00000188739.
Subcellular location: Nucleus, nucleolus
Subcellular location (Human Protein Atlas): Nucleoli; Mitotic chromosome; Nucleoplasm
Gene Ontology:
Molecular function: RNA binding; nucleic acid binding
Biological process: maturation of LSU-rRNA from tricistronic rRNA transcript (SSU-rRNA, 5.8S rRNA, LSU-rRNA)
Cellular component: nucleolus
Genetic constraint (gnomAD): Loss-of-function variants: 37 observed, 44.26 expected, observed/expected ratio (o/e) 0.84, 90% interval 0.64 to 1.1. The upper end of that interval is the gene's LOEUF score, 1.1, which puts it in group 4 of 6, group 1 being the genes least tolerant of losing a copy. Missense variants: 552 observed, 509.42 expected, observed/expected ratio (o/e) 1.08, 90% interval 1.01 to 1.16. Synonymous variants: 183 observed, 181.85 expected, observed/expected ratio (o/e) 1.01, 90% interval 0.89 to 1.14.
Homologues: Orthologues: chimpanzee RBM34 (98% identical), macaque RBM34 (93% identical), rabbit RBM34 (79% identical), dog RBM34 (77% identical), pig RBM34 (76% identical), guinea pig RBM34 (73% identical), mouse Rbm34 (70% identical), rat Rbm34 (69% identical), rat Rbm34-ps1 (60% identical), tropical clawed frog rbm34 (47% identical), zebrafish rbm34 (42% identical). Paralogues in human: PABPC4 (18% identical), PABPC1L (17% identical), PABPC1 (17% identical), PABPC3 (17% identical), SYNCRIP (16% identical), HNRNPR (15% identical), PABPC4L (15% identical), PABPC5 (13% identical), ELAVL2 (13% identical), ELAVL4 (12% identical), RBM45 (12% identical), ELAVL3 (12% identical), and 12 more.
Diseases named in the same sentence as RBM34 in open-access papers:
RBM34 is named in the same sentence as 9 diseases in open-access papers, as found by Europe PMC text mining. Sharing a sentence is not in itself a finding about the gene and the disease. The quoted sentences say what the papers report.
osteosarcoma (3 papers, 2021 to 2024). A usually aggressive malignant bone-forming mesenchymal neoplasm, predominantly affecting adolescents and young adults. "A risk score model constructed based on four epigenetic modification-related genes (MYC, TERT, EIF4E3, and RBM34) can effectively predict the prognosis of patients with osteosarcoma." (PMID 34853590, 2021). "Our results showed that compared with osteoblasts, CPEB3, EIF4E3, RBM34, RPS27L, RPS29 and TDRD6 were down-regulated in U2OS and 143B, while NXT2, TERT, TLR8 and ZC3HAV1 were up-regulated in osteosarcoma cells." (PMID 34926575, 2021).
hepatocellular carcinoma (1 paper, 2024). A malignant tumor that arises from hepatocytes. "RBM34 and RBM15 played an oncogenic function in hepatocellular carcinoma and PC progression, respectively." (PMID 39741300, 2024).
pancreatic cancer (1 paper, 2020). "However, there were also proteins that, to the best of our knowledge, have not yet been associated with oncogenic potential in pancreatic cancer, e.g., OAS proteins, RBM34 or DQX1." (PMID 32545414, 2020).
prostate carcinoma (1 paper, 2021). A carcinoma that arises from epithelial cells of the prostate gland. "The RNA-binding protein RBM34 has been shown to be overexpressed in recurrent prostate cancer." (PMID 34853590, 2021).
cancer (3 papers, 2021 to 2025). A tumor composed of atypical neoplastic, often pleomorphic cells that invade other tissues. "This comprehensive examination underscores the significance of RBM34 in modulating cancer progression and treatment outcomes." (PMID 40853971, 2025). "As for RBM34, no studies have been reported on its role in the progression of cancers." (PMID 36506302, 2022). "But so far, TDRD6, NXT2, RBM34 have not been described in cancer." (PMID 34926575, 2021).
tumor (3 papers, 2021 to 2024). "In addition to the factors mentioned, it is likely that other SFs identified here as having consistent changes across all tumor types (SNRPB, RNPS1, RBM34, ELAVL1, and RALYL) could contribute to tumor-associated splicing events in the analyzed datasets." (PMID 33621242, 2021).
infection (2 papers, 2025 to 2026). The state of being infected such as from the introduction of a foreign agent such as serum, vaccine, antigenic substance or organism. "Integration with RNA-seq data revealed key genes (IL1R2, RBM34, EDEM3, and MZB1) potentially critical in early infection." (PMID 42087228, 2026). "From the perspective of AFB1 exposure, regardless of infection status, four proteins—OBF1, RBM34, IGHM, and EBP2—decline more readily in response to AFB1 compared to the DMSO control." (PMID 41016387, 2025).
RBM34 also shares sentences with these, for which no sentence is quoted: bladder cancer (1 paper); breast carcinoma (1).